ENSG00000280371 ( gene)
Diseases named in the same sentence as ENSG00000280371 in open-access papers (continued):
Sharing a sentence is not in itself a finding about the gene and the disease.
tumor (continued). "In summary, our data indicate that microRNA-126 is a tumor-suppressor gene in NSCLC and low microRNA-126 expression is a significantly unfavorable prognostic factor in NSCLC patients." (PMID 22900072, 2012). "Loss of PLAGL1 expression is frequently observed in many human tumours, consistent with its proposed role as a tumour-suppressor gene." (PMID 22723905, 2012). "Recently, AHRR has been proposed to function as a putative new tumor suppressor gene based on some relevant studies in multiple types of human cancers." (PMID 22952704, 2012). "For example, in epidermis, Notch1 is a tumour suppressor gene that represses the Wnt/β-catenin pathway, while Wnt signalling is known to promote epidermis neoplasia." (PMID 22615875, 2012). "AKAP12/Gravin (A kinase anchor protein 12) is one of the A-kinase scaffold proteins and a potential tumor suppressor gene in human primary cancers." (PMID 21918680, 2011). "Infact, the same microRNA can act as an oncogene in one biological condition and as a tumor suppressor gene in another." (PMID 19513126, 2009). "Globally, KLF4 and KLF6 are considered as tumor suppressor gene, whereas KLF5 promotes cell proliferation." (PMID 20119532, 2009). "Carcinoembryonic antigen-related cell adhesion molecule 1 (CEACAM1), a cell adhesion molecule expressed in a variety of cell types is a putative tumor suppressor gene." (PMID 18507857, 2008). "Merlin, the product of the Neurofibromatosis type 2 (NF2) tumor suppressor gene, belongs to the ezrin-radixin-moesin (ERM) subgroup of the protein 4.1 superfamily, which links cell surface glycoproteins to the actin cytoskeleton." (PMID 16324214, 2005). "We subjected the promoter regions of two genes residing at 11p, namely the tumour-suppressor gene WT1 (Wilms' tumour gene) (11p13) and the calcitonin gene (11p15.5), to methylation analysis in human sporadic colorectal cancer using genomic sequencing." (PMID 9365158, 1997). "SORBS2 is a tumor-suppressor gene predominantly expressed in myofibroblasts." (PMID 41766902, 2026). "We found that low PLCG1 expression was associated with poor survival outcomes, which may function as a tumor suppressor gene in GBM." (PMID 40761791, 2025). "The JCHAIN plays an important role in tumour immunity as an immune-related gene." (PMID 41010015, 2025). "Multiple studies reported that HIF1A may function as a tumor suppressor gene, whereas EPAS1 acts as an oncogene." (PMID 39477683, 2025). "SIRT5 exhibits dual functionalities: it can promote tumor proliferation, metastasis, drug resistance, and metabolic reprogramming, thereby acting as an oncogene; conversely, it can also inhibit tumor cell growth and induce apoptosis, functioning as a tumor suppressor gene." (PMID 39944690, 2025). "The results of the miRNA microarray analysis suggest that DDX3 may function as an oncogene or a tumor suppressor gene by regulating the expression of a small subset of miRNAs." (PMID 39543456, 2025). "For instance, in particular cancer types, miR-155 acts as an oncogene; in others, it may serve as a tumor suppressor gene." (PMID 39963112, 2025). "PLIN1 is recognized as a tumor suppressing gene in multiple malignancies, such as HCC." (PMID 39870645, 2025). "In addition to regulating mitophagy, Ambra1 acts as a tumor suppressor gene in vivo; it inhibits cell cycle progression into the G1-S phase by promoting the degradation of cyclin D." (PMID 40141351, 2025). "Our objective was to investigate whether DEPDC1B functions as a tumor suppressor gene in COAD by influencing the immune microenvironment of tumors." (PMID 39087856, 2024). "In addition, DCA was significantly positively correlated with Lrmp (a tumor promotion gene), and TDCA was significantly positively correlated with Hnrnpa2b1." (PMID 38982226, 2024).
tumor (continued). "Notably, DCDC2 has been identified as a candidate tumor suppressor gene in HCC through triple combination array analysis." (PMID 38658618, 2024). "BCL2 is an apoptosis-inhibiting gene and is considered an influential factor in tumor cell production and proliferation, and it may play a role in the HF growth cycle and morphogenesis." (PMID 38674344, 2024). "In conclusion, our study highlights SMYD4 as a tumor suppressor gene across various solid tumors." (PMID 38892284, 2024). "PTEN is a tumor suppression gene that is commonly deleted at chromosome 10q23." (PMID 39156315, 2024). "It was found to facilitate tumor cell apoptosis and may be a tumor suppressor gene through involving the JAK/STAT1 pathway." (PMID 39737399, 2024). "Moreover, miR-671-5p was identified as a tumor suppressor gene, inhibiting HCC cell migration, invasion, and EMT." (PMID 38166853, 2024). "Findings of recent years indicate that RIPK3 is a tumor suppressor gene." (PMID 38397165, 2024). "PTPRM has an important role in tumorigenesis as a tumor suppressor gene." (PMID 37403117, 2023). "As a tumor-suppressor gene, JWA plays an important role in blocking pan-tumor progression." (PMID 37240137, 2023). "Another gene downregulated by ~nine-fold in GEN-treated TM4 cells is Usp18 (Ubiquitin specific protease 18), shown to promote proliferation and be negatively regulated by Wt1 (Wilms tumor gene), a transcription factor that plays a role in spermatogenesis and in inhibiting interferon signaling." (PMID 37443838, 2023). "Moreover, increasing evidence has shown that PER2 acts as a tumor suppressor gene to inhibit the proliferation of tumor cells." (PMID 37069338, 2023). "This could be explained by the fact that it acts as tumor suppressor gene and is consistent with the reported poor survival rates of reduced levels of microRNA-125a in different tumors." (PMID 36892621, 2023). "This in turn suggests that SEC23A itself might also act as a tumor-promoting gene, at least in STAD." (PMID 37046730, 2023). "MiR-485-5p has been identified as a tumor suppressor gene in various cancers." (PMID 37348024, 2023). "If the key target of the miRNA gene in a specific cell type is an oncogene, the miRNA gene can be considered a tumor suppressor gene; if the target of the miRNA gene is a tumor suppressor gene in different cell types, the miRNA gene can be considered an oncogene." (PMID 37371458, 2023). "Besides lung, CCNDBP1 has been proposed to be a tumor suppressor gene for multiple tissues, including prostate, breast, liver, ovary, lymph, retina, colon, neuroglial, bone and lens epithelial cell through interacting with different proteins." (PMID 37058478, 2023). "ASXL1 plays a role in chromatin remodelling and is a tumor suppressor gene." (PMID 37379307, 2023). "The GSE14333 dataset was used as the validation cohort to further validate the hypothesis that ZNF880 may function as a possible tumor suppressor gene in CRC in this study." (PMID 37370088, 2023). "Similar to NCCRP1, USP19 is aberrantly expressed in multiple cancers and may act as a tumour suppressor gene or oncogene, which relies upon the tumour type." (PMID 38106991, 2023). "Therefore, our findings suggest that miR-375 acts as a tumor suppressor gene in GC, which is consistent with previous studies." (PMID 38505381, 2023). "PRAME was found as a tumor-promoting gene in hematological system neoplasms." (PMID 36980687, 2023). "This miR leads to the downregulation of FOXO3a (the Forkhead transcription factor O subfamily), which normally acts as a tumour suppressor gene, increases OSCC chemoresistance for DDP, and is directly associated with aggressive progression and poor prognosis in cancers." (PMID 37242569, 2023). "Our findings indicate that KIAA1456 is a novel tumour suppressor gene and may be a possible therapeutic target in clinical practice." (PMID 37056382, 2023). "PP2A is an important regulator of signal transduction pathways and is a tumor suppressor gene." (PMID 36975444, 2023).
tumor (continued). "Evidence shows that NCCRP1 plays an essential role in tumour development, and whether it acts as a tumour suppressor gene or oncogene depend upon tumour types." (PMID 38106991, 2023). "RUNX1 is a member of the RUNX family of transcription factors (RUNX1, RUNX2 and RUNX3), and is known to influence the malignancy of many neoplasms, including leukaemia, and to act as an oncogene or tumour suppressor gene with diverse functions depending on the tumour." (PMID 36085167, 2022). "Until recently, researchers found LHPP function as a tumor suppressor gene in multiple cancers." (PMID 36484014, 2022). "ACSL3 has a favorable correlation with CTNNB1, a recognized tumor-promoting gene." (PMID 36338658, 2022). "PTTG1 is a tumour transforming gene, which can cause cell transformation without the participation of any auxiliary gene, and is closely related to the occurrence of many tumours." (PMID 35037540, 2022). "NRF2 was considered to have two sides to its roles, it may play as either an oncogene or a tumor suppressor gene based on different cellular environments." (PMID 35163707, 2022). "However, most reports demonstrated that this miRNA is a tumor suppressor gene with lower expression in diverse cancers." (PMID 35444696, 2022). "It potentially suggested that miR-149 may play a role as a tumor suppressor gene in the Hp-induced pathological evolution of gastric mucosa." (PMID 36712871, 2022). "In addition to its involvement in neuropsychiatric disorders, EGR1 has also been widely examined in the field of cancer where it plays paradoxical roles as a tumor suppressor gene or oncogene." (PMID 36338037, 2022). "miR-323a-3p is located on chromosome 14q32.31 and acts as a tumor suppressor gene in CRC." (PMID 35096064, 2022). "In addition, as a potential tumor suppressor gene, C2orf40 inhibits the expression levels of cell cycle-related proteins (CCNE1 and CDK1), and blocks the cell cycle in G2/M phase." (PMID 35676661, 2022). "Indeed, in the context of neoplasm, E‐cadherin has long been proved as a tumor‐suppressor gene inhibiting cancer initiation and progression." (PMID 35601657, 2022). "CPNE1, a tumor-related gene, plays the role of proto-oncogene to promote tumor development." (PMID 35139863, 2022). "SMAD4 is a tumor-suppressor gene, acting as a downstream regulator of the TGF-β pathway." (PMID 35049691, 2022). "A recent study proposed that ZNF395 is a novel tumor suppressor gene." (PMID 36139015, 2022). "CHD5 has previously been reported to be a potential tumor suppressor gene in various solid tumors." (PMID 35955624, 2022). "Together, these results suggest that NEDD4L acted as a tumor suppressor gene in LUAD." (PMID 35090513, 2022). "FOXO3 is commonly regarded as a tumor-suppressive gene in cancer." (PMID 34795388, 2022). "A substantial number of studies have reported that AURKB is a tumor-related gene." (PMID 35088239, 2022). "These contradictory reports suggest that FAM198B may play dual roles, i.e. as an oncogene role or as a tumor suppressor gene in different cancer contexts, possibly also indicating that FAM198B may have different effects in different cells." (PMID 35587159, 2022). "Meg3 is a maternally expressed imprinted gene that functions as a lncRNA tumor suppressor." (PMID 35664469, 2022). "MiR-21-5p has been testified to be a tumor suppressor gene with decline in multiple cancers." (PMID 35191804, 2022). "The study reported that GADD45G might act as a tumor suppressor gene and upregulation inhibits cell proliferation." (PMID 34299042, 2021). "Published data confirmed that miR-145 may be a tumor suppressor gene expressed in a variety of tumor tissues (including ovarian cancer, cervical cancer, breast cancer and colorectal cancer), and its expression level is significantly lower than normal tissues." (PMID 33407764, 2021). "PTEN, a tumor suppressive gene, was identified as a direct target gene of miR-4461 in OC cells." (PMID 33767986, 2021).
tumor (continued). "Some reports suggest that miR-137-3p acts as a tumor suppressor gene in cancer." (PMID 33968763, 2021). "We found that miR‐378a‐3p acted as a tumor‐suppressor gene in HCC." (PMID 33634974, 2021). "These previous findings suggested that Spred2 function as a potential tumor suppressor gene." (PMID 34818323, 2021). "Interestingly, ATF3 can act as an oncogene or as a tumor suppressor gene, depending on the type of tumor and the cellular context." (PMID 33539340, 2021). "Additionally, NFAT1 was also found to act as a tumor suppressor gene to block cell cycle progression by directly regulating cyclin E expression in B lymphocytes." (PMID 34257525, 2021). "S100A4 is a well-known tumor promoting gene and is the most studied one in HCC." (PMID 33815482, 2021). "The studies confirmed the hypothesis that CLU could indeed act as a tumor suppressor gene by knockout of the CLU gene." (PMID 33299887, 2020). "We identified a tumor suppressive gene p21, which involves in cell cycle progression." (PMID 32393761, 2020). "Phosphatase and tensin homolog (PTEN) acts as a tumor suppressor gene." (PMID 32134893, 2020). "The lactoferrin (LTF) gene, located at 3p21.3, acts as a tumor suppressor gene in diverse tumors." (PMID 33585219, 2020). "In other words, miR-375 plays a similar tumor suppressor gene." (PMID 32382558, 2020). "Altogether, our data support a role of BDH2 as a tumour-suppressor gene in NPC." (PMID 31819181, 2020). "The genetic data and the IHC analysis of ESCC samples indicated that ZNF750 might act as a tumor suppressor gene in ESCC." (PMID 32042337, 2020). "Accumulating studies have reported that the dysregulation of miR-214 is causative for carcinogenesis, which may function as either an oncogene or a tumor suppressor gene dependent on specific types of tumor." (PMID 31058093, 2019). "Because GOS2 has pro-apoptotic activity and it is epigenetically repressed or down-regulated in human cancers, it could be described as a tumor-suppressor gene." (PMID 31590218, 2019). "Our previous study identified CACNA2D3 as a novel tumor suppressor gene for ESCC." (PMID 31001468, 2019). "Evidence has demonstrated that miR-183 plays an essential role in tumorigenesis, which could serve as either an oncogene or a tumor-suppressor gene in different types of cancer." (PMID 31210063, 2019). "Our findings indicate that the chimeric transcript SEPT7P2-PSPH is a product of trans-splicing of two adjacent genes and might be a tumor suppressor gene, potentially having the role of anticancer activity." (PMID 31057610, 2019). "Furthermore, it was reported UPF1 acts a tumor suppressive gene in HCC, but, the role played by UPF3A, in the pathogenesis of HCC, has not been well studied." (PMID 31856847, 2019). "NFIB can also act both as an oncogene and a tumor suppressor gene depending on the tumor type." (PMID 31426421, 2019). "It has been reported that ALDH1A2 is a candidate tumor suppressor gene in prostate cancer." (PMID 30944378, 2019). "RASAL2, a unique RAS GTPase-activating protein (RAS-GAP), has been reported as a tumor-suppressor gene, which inhibits tumor progression in different types of cancer, such as luminal B breast cancer, ovarian cancer, lung cancer, nasopharyngeal carcinoma, and colorectal cancer." (PMID 30158581, 2018). "However, the idea that the same tumor gene can be classified as an oncogene or a tumor-suppressor gene, depending on the physiologic context, has been previously raised." (PMID 30297765, 2018). "In a previous research, we demonstrated that EYA4 expression is down-regulated in human HCC tissue and that its suppression is an independent prognostic factor of poor survival, which suggests EYA4 might be a potential tumor suppressor gene in HCC." (PMID 29764501, 2018). "Post irradiation the contrasting expression profiles of PARTICLE and WWOX in such cell lines that represented various WWOX genetic backgrounds suggest a relationship may exist between this lncRNA and this tumor suppressor gene." (PMID 29152092, 2017).
tumor (continued). "Our results revealed that miR-29a-3p is a tumor suppressor gene that acts by directly repressing the oncogene IGF1R, which takes part in immunoregulation in tumor microenvironments in HCC, implying that miR-29a-3p could be a potential target for HCC treatment." (PMID 29156819, 2017). "In addition to being able to function as an oncogene, many studies have demonstrated that miR-27a can also play an essential role as a tumor-suppressor gene in the development and progression of various cancer." (PMID 28415619, 2017). "Together, these studies congruously characterized ANGPTL1 as a tumor suppressor gene in cancer." (PMID 28606130, 2017). "These GPAT2-induced changes are consistent with its proposed function as a tumor-promoting gene, and might be used as a phenotypic differentiation marker." (PMID 29211789, 2017). "Death-associated protein kinase (DAPK), a tumor suppressor gene, could mediate cell death in INF-γ–induced apoptosis, whereas inactivated DAPK, could lead to the pathogenesis and metastasis of the tumor." (PMID 28249042, 2017). "The E- cadherin is tumor suppression gene that regulates epithelial cell behavior." (PMID 28824426, 2017). "miRNAs may act as a tumor suppressor gene or oncogene, and may regulate tumor invasion and metastasis such as the EMT." (PMID 29262657, 2017). "In this regard, miR-424 often plays a role as tumor suppressor gene." (PMID 28928430, 2017). "Thus, AHRR has been proposed to function as a putative new tumor suppressor gene in multiple types of human cancers." (PMID 28056099, 2017). "Phosphatase and tensin homolog (PTEN) is a tumor-suppressor gene." (PMID 27936183, 2016). "Mounting evidence has demonstrated that miR-506 is a tumor suppressor gene." (PMID 27542202, 2016). "PTEN is deemed as a tumor suppressor gene that negatively regulates PI3K/Akt signaling." (PMID 27713121, 2016). "P21 is a well-recognized cell cycle inhibitor and a tumor suppressor gene." (PMID 27905892, 2016). "In this study, we demonstrated that miR-218-5p was downregulated in NSCLC tissues and could suppress cell proliferation and migration in vitro and retard tumor growth in vivo, which suggests a role for miR-218-5p as a tumor suppressor gene in NSCLC." (PMID 27057632, 2016). "Indeed, it has been observed that WT1 can act as a tumor suppressor gene or, in some cases, as oncogene by considering the tumor histotype." (PMID 27014421, 2016). "It has been suggested that the CpG island methylation observed may silence specific tumour-related genes, including the mismatch repair gene MLH1, which may give rise to microsatellite instable tumours." (PMID 27279102, 2016). "Our results demonstrate that miR-203 serves as a tumor suppressor gene and may be useful as a new potential therapeutic target in CRC." (PMID 27376958, 2016). "In our study, KLF4 and IRF8 were up-regulated TFs, and IRF8 was a tumor suppressor gene." (PMID 27405725, 2016). "Collectively, our findings indicated that Sesn2 may act as a tumor suppressor gene that can inhibit cancer cell proliferation viability through the regulation of Akt-mTOR-p70S6K signal pathway." (PMID 25962159, 2015). "It was proposed that the IGFBP-3 gene could be a putative tumor suppressor gene and/or therapeutic target for human cancers." (PMID 26370590, 2015). "DLEU2 is thought to be a tumor-suppressor gene as it is frequently deleted in malignant tumours." (PMID 25822729, 2015). "Smad4 is a tumor-suppressor gene with a key role in the TGF-β signaling pathway." (PMID 25890228, 2015). "Their results supported the idea that CSMD1 was a tumor suppressor gene." (PMID 26076954, 2015). "Based on that, miR-601 could serve as a putative tumor suppressor gene, whilst miR-34a as an oncogene." (PMID 25551588, 2014). "Since miR-30b was either up-regulated or reduced in different cancers, we could draw a conclusion that miR-30b may play different roles as an oncogene or a tumor suppressor gene in various cancers." (PMID 25170877, 2014).